ESR1 (estrogen receptor 1)
Diseases named in the same sentence as ESR1 in open-access papers (continued):
Sharing a sentence is not in itself a finding about the gene and the disease.
liver cancer (continued). "When exploring the core genes’ expression in the GEPIA database, we found that ESR1 gene expression was significantly reduced in liver cancer patients, while SRC gene expression was significantly increased in liver cancer compared to healthy people." (PMID 40508014, 2025). "Robust positive correlations are evident with key hormonal markers such as AR (ρ = 0.668), ESR1 (ρ = 0.547), and THRB (ρ = 0.424), underscoring the intricate involvement of SELENOP in hormonal pathways within the realm of liver cancer." (PMID 39001444, 2024). "The stage plot analysis further highlights the dynamic nature of these genes across different cancer stages, particularly in liver cancer, where CYP3A4, ESR1, and CYP19A1 showed significant changes." (PMID 39204124, 2024). "As a result, ESR1 and EGFR were identified as potential core targets of CKI for treating liver cancer and were selected for a subsequent experimental analysis." (PMID 39457402, 2024). "Statistically significant variations (p < 0.05) were observed in the expression levels of CYP3A, ESR1, and CYP19A1 across different stages of liver cancer." (PMID 39204124, 2024). "The results indicated that the key targets of the pathway in cancer were related to the therapeutic effect of anti-liver cancer activities, including SRC, EGFR, ESR1, PTGS2, and APP." (PMID 36561345, 2022). "Previous studies found that ESR1 functions as a tumor suppressor gene in HCC and mediates apoptosis of liver cancer cells." (PMID 36193154, 2022). "The in-vitro data indicated that intracellular contents of ESR1, EGFR mRNAs in oxyresveratrol-treated liver cancer cells were reduced." (PMID 34592904, 2021). "These validated findings demonstrated that the ESR1, EGFR can be anti-liver cancer pharmacological targets exerted by oxyresveratrol." (PMID 34592904, 2021). "Among these, the expression levels of ESR1,SPP1 and FOSB genes were closely related to the survival time of liver cancer patients." (PMID 34238253, 2021). "In addition, ESR1 may play a role in the development and prognosis of liver cancer." (PMID 34055017, 2021). "The results showed that among these Hub Genes, the expression levels of ESR1, SPP1 and FOSB genes was closely related to the survival time of liver cancer patients, with statistically significant differences (p < 0.05)." (PMID 34238253, 2021). "Esr1 has been shown to suppress proliferation, migration, and invasion in liver cancer cells; its underexpression predicts a worse prognosis in HCC patients; and female liver cancers specifically upregulate a miRNA that reduces Esr1 expression." (PMID 34068249, 2021). "Therefore, changes in the expression levels of ESR1, FOBS and SPP1 genes in liver cancer inhibited all three pathways." (PMID 34238253, 2021). "Finally, single-gene GSEA analysis was performed on the three prognostic genes, ESR1, SPP1 and FOSB, that affect the survival time of liver cancer patients in order to explore the mechanism affecting the prognosis of liver cancer patients." (PMID 34238253, 2021). "Following with experimental verification, the identified genes of ESR1, EGFR may function as potential screening anti-liver cancer markers." (PMID 34592904, 2021). "To verify whether ESR1 expression can affect the YAP pathway, we established an ERα overexpression system in liver cancer cell lines (HepG2 and Hep3B) that have lower expression levels of ESR1." (PMID 34145394, 2021). "Specific to the luminal A comparison was the gene CCND1 (oncogene; breast and pan-cancer), the second most interconnected after ESR1 (oncogene; breast and pan-cancer), while ELOVL6 (oncogene; liver cancer) was the most interconnected unique gene within the luminal B vs TNBC network." (PMID 32605588, 2020).
liver cancer (continued). "Interestingly, BNC1 is also a putative ER receptor 1 (ESR1) target as ESR1 was bound in the proximal promoter of BNC1 in T-47D cell line (ENCODE data on UCSC genome browser), raising the possibility that BNC1 might also play a role in sexual dimorphism in liver cancer similar to FOXA1." (PMID 28673244, 2017). "In addition, GEPIA online analysis showed that ESR1, AR, CCNB1, CDK1, AKR1C3 and CCNA2 might become potential target genes for the survival and prognosis of PADP for the treatment of liver cancer." (PMID 35463358, 2022). "BNC1 is also a putative ESR1 target as ESR1 was bound in the proximal promoter of BNC1 in T-47D cell line, raising the possibility that BNC1 may also have a role for sexual dimorphism in liver cancer." (PMID 28673244, 2017).
metabolic syndrome (56 papers, 2011 to 2026). A cluster of metabolic risk factors for CARDIOVASCULAR DISEASES and TYPE 2 DIABETES MELLITUS. "Estrogen is implicated in the skeletal muscle metabolism because muscle ERα mRNA (ESR1) level was decreased in women who suffered from metabolic syndrome and it was inversely associated with adipose tissue mass and fasting insulin level." (PMID 36768177, 2023). "Recent research has reported that variants in ESR1 have a significant role in developing T2D and metabolic syndromes; however, the results were conflicting." (PMID 35627115, 2022). "ESR1 Xbal G alelle was associated to insulin sensitivity and metabolic syndrome in the Study of Women’s Health Across the Nation, but only in Asian ones." (PMID 25077953, 2014). "Furthermore, ESR1 Xbal polymorphism was associated to metabolic syndrome in 548 individuals from 42 African-American families from the Insulin Resistance Atherosclerosis Family Study (OR = 1.53; 1.05–2.27, p = 0.029)." (PMID 25077953, 2014). "The aim of this study was to investigate the association and interaction of metabolic syndrome (MetS) and estrogen receptor alpha 1 (ESR1) gene polymorphisms on cardiovascular autonomic neuropathy (CAN)." (PMID 27453734, 2016). "Oestrogen is linked to skeletal muscle metabolism, as evidenced by a decrease in muscle ERα mRNA (ESR1) levels in women with metabolic syndrome." (PMID 40045692, 2025). "Moreover, a rare inactivating mutation of ESR1 (the gene encoding ERα) was shown to produce metabolic dysfunction in a middle-aged man, and male mice with a homozygous Cyp19 (encodes aromatase) or Esr1 null deletion mutation recapitulate many clinical features of metabolic syndrome." (PMID 40328250, 2025). "The ESR1 and ESR2 genotypes are associated with insulin sensitivity and metabolic syndrome in Japanese and Chinese women." (PMID 33777160, 2021). "We observed that acute liver-specific disruption of ESR1 increases the expression of key gluconeogenic and lipogenic enzymes which also resulted in increased gluconeogenesis and dyslipidemia." (PMID 28490809, 2017). "Specifically, estrogens, via ESR1, promote dyslipidemia by inhibiting bile acid secretion and interfere with hepatocyte uptake." (PMID 29326659, 2017). "Decreased ESR1 expression level can lead to conditions such as dyslipidemia and steatosis." (PMID 38726425, 2024). "The upregulation of ESR1 in utero may be the basis for the burst of metabolic syndrome dysfunctions occurring during the peri-pubertal transition into adolescence and beyond." (PMID 29326659, 2017). "Impaired hepatic E2 action in male mice, produced by hepatic specific Esr1 ablation, could recapitulate aspects of the metabolic syndrome." (PMID 28490809, 2017). "Thus, ubiquitous knockout of Esr1 results in a phenotype similar to that of metabolic syndrome." (PMID 35203717, 2022). "In the liver ESR1 modulates hepatic cholestasis (network 5), FXR/RXR, and LXR/RXR (network 1) pathways that control bile acid turnover, regulate lipid and cholesterol metabolism leading to dyslipidemia." (PMID 29326659, 2017). "Finally, expression of Esr1 was repressed in LCR-100 in comparison to HCR-100 and its down-regulation may reflect the metabolic syndrome in LCR-100." (PMID 35203717, 2022).
osteosarcoma (54 papers, 2005 to 2025). A usually aggressive malignant bone-forming mesenchymal neoplasm, predominantly affecting adolescents and young adults. "Although there were fewer studies on ESR1 and osteosarcoma, ESR1-mediated estrogen effects associated with bone mineralization have been reported." (PMID 36466554, 2022). "One of the mechanisms associated with the poor prognosis of osteosarcoma was abnormal ESR1 methylation." (PMID 36466554, 2022). "Variants in ESR1 could be important in osteosarcoma since estrogen is critical during puberty which is the key time of risk for osteosarcoma." (PMID 21437228, 2011). "As a representative of this functional group, ESR1 has been described as a tumor suppressor gene in various cancers, including osteosarcomas." (PMID 40790102, 2025). "Among these core targets, EGFR (48-sided), CASP3 (47-sided), ESR1 (42-sided), HSP90AA1 (42-sided), SRC (42-sided) and IGF1 (40-sided) have high nodes, indicating that they are closely associated with PA anti-osteosarcoma dense mechanisms." (PMID 40991530, 2025). "According to the expected core targets of the PPI network that were significantly associated with anti-osteosarcoma effects, the top five target proteins (EGFR, Caspase-3, ESR1, HSP90AA1, and SRC) ranked by degree value were subjected to molecular docking." (PMID 40991530, 2025). "Ospemifene has thus far been tested on the U2OS osteosarcoma line, where similar to our results, the protective effect of ospemifene against etoposide-induced apoptosis was mediated primarily by ESR1." (PMID 37129835, 2023). "In a second study, the same group hypothesized that variants in the estrogen receptor (ESR1), vitamin D receptor (VDR), and/or collagen 1α1 (COL1A1) gene could be osteosarcoma risk factors." (PMID 21437228, 2011). "Moreover, formononetin could reduce the expression of ESR1 in osteosarcoma and inhibit cell proliferation." (PMID 35463082, 2022). "PPI results showed that EGFR, CASP3, ESR1, HSP90AA1, and SRC may be potential targets for PA against osteosarcoma." (PMID 40991530, 2025).
Hypertension (52 papers, 2012 to 2025). The presence of chronic increased pressure in the systemic arterial system. "Two DEGs (Esr1 and Hif3a) encoding transcription factors and associated with hypertension were identified." (PMID 38928385, 2024). "ESR1 mediates the physiological functions of estrogen and is associated with arterial hypertension, changes in blood lipid levels, coronary atherosclerosis, and changes in HDL-C levels in postmenopausal women." (PMID 38920980, 2024). "Polymorphic alterations of ESR1 are associated with conditions such as arterial hypertension, altered serum lipid levels, coronary atherosclerosis, and altered HDL-C levels in menopausal women." (PMID 35722157, 2022). "Single-nucleotide polymorphisms in the ESR1 gene have been associated with vascular diseases and conditions, such as arterial hypertension, CVD, cerebrovascular disease, and serum lipid level alterations." (PMID 32190085, 2020). "The N-terminus of ESR1 plays a critical role in activating ESR1-reliant genes, and any mutations in this location have been associated with high blood pressure." (PMID 30630878, 2019). "The first four of these genes are associated with hypertension, with the Esr1 gene encoding a TF." (PMID 38928385, 2024). "The genetic association has been described for SNPs in the ESR1 gene with various pathological conditions, including CVD, T2D, hypertension, and lipoprotein metabolism." (PMID 26370976, 2015). "In our data, Esr1 (transcript encoding ER-α) is upregulated in the adrenal gland and lung in female SHR, which may account for the lower incidence of hypertension reported previously in premenopausal females as compared to males." (PMID 39514592, 2024). "Finally, the TF (HAND1, E4BP4, ESR1, VBP, ELK-1, POU3F2) associated with LV remodeling in hypertension were confirmed to act a crucial role in correlated heart diseases." (PMID 32664164, 2020). "In addition, from the point of view of the score, the score of VEGFA, ESR1 is higher, which may play an important role in the treatment of hypertension in P. ternata." (PMID 34062719, 2021). "The occurrence of hypertensive disorder complicating pregnancy can be caused by the decrease of the expression of MMP9 in the network, and AKT1, ESR1, FOS, VEGFA and other proteins play an important role in the pathogenesis of hypertensive disorder complicating pregnancy, such as preeclampsia." (PMID 34062719, 2021).
type 2 diabetes (50 papers, 2005 to 2025). "Dysregulation of ESR1 expression or function has been linked to an increased risk of type 2 diabetes and its complications." (PMID 40800999, 2025). "Previously, an African-American case-control study detected an association between a region of the ESR1 gene and type 2 diabetes." (PMID 35990823, 2022). "At the same time, polymorphisms in the ESR1 gene are associated with type 2 diabetes and with fasting plasma glucose." (PMID 33980847, 2021). "Variants in ESR1 have been associated with many traits including type 2 diabetes in African Americans, and HDL-C response to atorvastatin in women." (PMID 24116192, 2013). "Gene association studies have so far identified 16 candidate loci involved in PCOS, including genes involved in gonadotropin action (LHCGR and FSHR), metabolism and sexual development (ESR1), insulin signaling and type 2 diabetes (INSR, THADA, HMGA2) or cell proliferation (YAP1 and SUMO1P1)." (PMID 40551954, 2025). "The present study suggests that the PvuII polymorphism in the ESR1 gene is associated with increased risk of type 2 diabetes but not with lipid profile." (PMID 31293826, 2019). "In type-2 diabetes cases, the circuit of ESR1, BRCA and CYP19 genes does not show mutation and the upregulation of estrogen signaling may easily compensate the difficulties of glucose uptake circuit." (PMID 41514592, 2025). "TF network analysis uncovered four upstream hub transcriptional factors NF-κB, ESR1, STAT3 and CTNNB1 active in both type 2 diabetes and hIAPP islets." (PMID 34554282, 2022). "Key mediators of the injury responses in islets transgenic for human IAPP or those from individuals with type 2 diabetes include STAT3, NF-κB, ESR1 and CTNNB1 by transcription factor analysis and COL3A1, NID1 and ZNF800 by gene regulatory network analysis." (PMID 34554282, 2022). "E2 acts through estrogen receptors ESR1 and ESR2, and they potentially affect development of type 2 diabetes (T2D)." (PMID 39833659, 2025).
lupus (49 papers, 2008 to 2024). "Recent studies demonstrating that ESR1 promotes SLE in F1-generation female mice of the lupus mouse model lend weight to this idea." (PMID 38835801, 2024). "For osteonecrosis of the femoral head, aberrant expression of CCND1 has been also found in the patients with osteonecrosis of the femoral head induced by systemic lupus erythematosus, and ESR1 may involve the osteonecrosis development of the children with acute lymphoblastic leukemia." (PMID 35035862, 2022). "To further investigate the mechanism of SIRT1 and ESR1 involvement in lupus pathogenesis, we analyzed SIRT1 and ESR1 using GSEA and also found that SIRT1 and ESR1 were involved in many biological processes of immune cells, which had been demonstrated in SLE." (PMID 38835801, 2024). "One study has identified the estrogen receptor alpha (ER-α) gene (ESR1) as a target induced by both IFNα and IFNγ in distinct cell types, including splenic cells, from lupus mice." (PMID 34733276, 2021). "Further evidence that ESR1, not ESR2, produces the lupus phenotype can be found in male mice lacking functioning ESR1." (PMID 38835801, 2024). "Treatment of splenocytes from C57Bl/6 or lupus-prone NZB/W mice and murine cell lines with either IFN-α or IFN-γ led to increased expression of ERα mRNA and protein levels, via transcriptional activation of the Esr1 promoter through STAT1." (PMID 30337927, 2018). "ESR1, TNF, SRC, HSP90AA1, and CASP3 further contribute to immunoregulation via distinct mechanisms: ESR1 influences the activity of T and B cells and plays a role in the treatment of sex-related autoimmune diseases, such as rheumatoid arthritis and systemic lupus erythematosus." (PMID 39717552, 2024).
Alzheimer disease (48 papers, 2009 to 2026). A progressive, neurodegenerative disease characterized by loss of function and death of nerve cells in several areas of the brain leading to loss of cognitive function such as memory and language. "Other Esr1 mutations have been linked to osteoporosis, breast cancer, and Alzheimer’s disease (AD) in females." (PMID 37425648, 2023). "The dysfunction of ESR1 will lead to neuroinflammation and further increase the risk of Alzheimer’s disease." (PMID 38005265, 2023). "Among the 29 TFs activated in male PD patients, ADNP, JUN, MBD3, PRDM14, and ESR1 have known associations with neurodegenerative disorders such as Alzheimer's disease, mental retardation, schizophrenia, and autism." (PMID 36414996, 2022). "Interaction of ESR1 with nutrients, such as vitamin D, regulates molecular pathways associated with Alzheimer’s disease development." (PMID 31836762, 2019). "Amyloid beta (A4) precursor protein, coagulation factor II (thrombin), and estrogen receptor 1 are involved mostly in Alzheimer disease, blood coagulation, and reproduction." (PMID 34466480, 2019). "However, even the exact role of ESR1 in Alzheimer’s disease is still not fully understood and more research is needed to elucidate its precise mechanisms." (PMID 39596595, 2024). "Danazol and miconazole target ESR1 and NOS3, both associated with Alzheimer’s disease." (PMID 31481665, 2019). "The relationships between ESR1 and cognitive impairment tend to be specific to or driven by women and restricted to risk for Alzheimer’s disease rather than other dementia causes." (PMID 30577643, 2018). "While the genes ESR1, GSTO1, and AGER have been studied in relation to Alzheimer’s disease, the exact mechanisms by which they contribute to the development and progression of the disease are still not fully understood." (PMID 39596595, 2024).